IL1RL1 (interleukin 1 receptor like 1)
Diseases named in the same sentence as IL1RL1 in open-access papers (continued):
Sharing a sentence is not in itself a finding about the gene and the disease.
Stroke (1 paper, 2026). Sudden impairment of blood flow to a part of the brain due to occlusion or rupture of an artery to the brain. "We present data showing that in rodents pericytes increase transcript expression predominantly for soluble IL1RL1 in inflammatory and stroke models." (PMID 41857656, 2026). "We also examine pericyte expression of both IL1RL1 transcripts using RNAscope in two different in vivo models of neuroinflammation, experimental autoimmune encephalitis (EAE) and photothrombotic stroke." (PMID 41857656, 2026).
xerosis (1 paper, 2023). "Similarly, the IL-33 receptor subunit IL1RL1 (ST2) is also expressed by dorsal root ganglion (DRG) neurons and was found to mediate itch associated with contact dermatitis and xerosis in mice." (PMID 37868811, 2023).
tumor (40 papers, 2013 to 2025). "It was found that Amphiregulin couples IL1RL1+ Tregs and cancer-associated fibroblasts to hinder anti-tumor immunity." (PMID 38604154, 2024). "We next looked at how IL1RL1 deficiency regulated the accumulation and activation of Treg cells in the tumor." (PMID 37611111, 2023). "Our data showed that the deletion of IL1RL1 on Treg cells shifted tumor-associated myeloid cells away from an immunosuppressive phenotype." (PMID 37611111, 2023). "Of note, tumor Tregs highly expressed IL1RL1 and IL1RN, which have been associated to inhibition of IL-1-mediated inflammation." (PMID 32601304, 2020). "We next investigated whether IL1RL1 deficiency on Treg cells also resulted in changes to tumor-associated myeloid cells." (PMID 37611111, 2023). "This was caused by decreased tumor cell proliferation in Il1rl1-deficient mice." (PMID 28119694, 2016). "Considering the tissue-specific nature of Il1rl1+ Treg cells, our findings support a novel approach for dual targeting within the local tumor microenvironment." (PMID 40659660, 2025). "Following a 10-dose regimen, we analyzed the effects of anti-murine Il1rl1 T-BsAb on the suppressive tumor microenvironment and on the leukemic cells." (PMID 40659660, 2025). "To further evaluate the on-target, off-tumor toxicity, we tested a broad panel of normal human tissues by staining human anti-IL1RL1 antibody at two different concentrations." (PMID 40659660, 2025). "Deregulation of the IL1RL1 activation state in TIICs was an effective measure to remodel the anti-tumor response." (PMID 38604154, 2024). "In studies of IL-33 in the context of cancer, Il33−/− mice and Il1rl1−/− mice have been shown to have greater tumor growth." (PMID 38825642, 2024). "Treatment of MC38 tumors with four rounds of IL-33 increased the accumulation of IL1RL1+ Treg cells in the tumor." (PMID 37611111, 2023). "Collectively, our data showed that IL1RL1+ Treg cells coupled with CAFs via an AREG/EGFR axis to promote tumor immunosuppression." (PMID 37611111, 2023). "CD44, a putative tumor stem cell marker, was significantly associated with C7, CXCL6, CLEC1B, and GPR182 in Hep3B cells and with C7, CXCL6, CLEC1B, and IL1RL1 in Huh7 cells." (PMID 36307751, 2022). "The IL1RL1/IL-33 axis can remodel the tumor stroma or microenvironment to promote malignancy by recruiting a cohort of immune cells." (PMID 34610582, 2021). "Compared to wild-type animals, Tregs from stage 1 show reduced expression of Klrg1 and Il1rl1, two markers of tissue resident Tregs, suggesting an early influx of Tregs from the circulatory system preceding tumour formation." (PMID 33686070, 2021). "The presence of IL1RL1+ Treg cells in the tumor promotes tumor progression." (PMID 37611111, 2023). "Yet, the mechanisms—specifically the target cell types and molecular interactions—used by IL1RL1+ Treg cells to alter the tumor microenvironment (TME) and promote tumorigenesis remain unknown." (PMID 37611111, 2023). "Notably, ligand/receptor pairs such as Il33/Il1rl1 (St2) and Cxcl12/Cxcr4 not only were abundant in tumors but also detected in cultured tumor cells." (PMID 35902768, 2022). "Furthermore, cluster 1 exhibited increased expression of IL1R2 and the IL-33 receptor ST2 (IL1RL1), which enhances the proportion and suppressive potential of tumor-infiltrating Treg in HNSCC patients." (PMID 33602930, 2021). "These pro-tumor effects of IL-33 are mainly mediated by IL-33 receptor ST2 (also known as IL-1RL1)." (PMID 30547011, 2018). "Interleukin-1 receptor-like 1 is the cognate receptor for interleukin-33, an epithelial-derived cytokine which has been reported to confer both pro- and anti-tumorigenic effects, depending on the tumour and cellular context, expression levels, and the nature of the inflammatory environment." (PMID 38301482, 2024). "We next tested whether IL1RL1 on Treg cells affected immune responses in the tumor." (PMID 37611111, 2023).
tumor (continued). "A number of fast evolving, placental genes show tumorigenic or tumor suppression activity (ADAM12, ADAMTS18, CAPN6, EGFL6, HTRA4, LIN28B) and others are involved in disorders associated with epithelial and connective tissues (FBN2) or have immune functions (IL1RL1, PRG2, SIGLEC6)." (PMID 26641094, 2015). "Further analysis of the differential expression of IL-1 family and related genes in normal tissues and HPV- and HPV+ tumor tissues revealed that IL-1α, IL-1β, IL1R1, IL1R2, IL1RL1, IL1RAP, IL1F10, IL-18 and CASP1 were highly expressed in HPV- tumors." (PMID 39461030, 2024). "According to the statistical results, the proportions of FGFBP2+ NK cells, IL1RL1+ T cells, CTLA4+ T cells, Myeloid cells 1, and Plasma B cells were higher than that of normal in tumor tissues." (PMID 38604154, 2024). "To determine the role of Areg in mediating IL1RL1+ Treg and CAF cross-talk and antitumor immunity, we treated B16–IL-33 tumor-bearing mice with an anti-AREG mAb." (PMID 37611111, 2023). "To determine the target cells of IL1RL1+ Treg–derived AREG in the TME, we looked in our whole tumor scRNA-seq data to see which cell types expressed Egfr, the only known receptor for AREG." (PMID 37611111, 2023). "IL1RL1 inhibits proliferation and metastasis of CRC through modification of the tumor microenvironment." (PMID 31695792, 2019). "Corresponding results were obtained by overexpressing or downregulating IL1RL1 in NSCLC cells, thereby showing that the IL-33-driven tumor progression in this model relies on ST2." (PMID 28119694, 2016). "Together, these data suggest that targeting the IL-33/Il1rl1 signaling pathway could be a therapeutic strategy for AML through dual inhibition of the LSCs and the inhibitory tumor microenvironment." (PMID 40659660, 2025). "In tumor tissues, IL-1α, IL-1β, IL1R1, IL1RL1, IL1F10, IL33, CASP1, and AIM2 are highly expressed." (PMID 39461030, 2024). "Whole tumor single-cell RNA sequencing (scRNA-seq) analysis and blockade experiments revealed that the amphiregulin (AREG)–epidermal growth factor receptor (EGFR) axis mediated cross-talk between IL1RL1+ Treg cells and CAFs." (PMID 37611111, 2023). "IL33/ IL1RL1 signaling can also promote the accumulation of tumor-infiltrating regulatory T-cells in the TME, suggesting that IL1RL1 may be a novel target for cancer immunotherapy." (PMID 37310469, 2023). "The sub‐clustering of ECs revealed six subtypes, including extra‐alveolar capillary EC (cEC) (FCN3+EDN1+PLVAP+), alveolar cEC (HPGD+EDNRB+IL1RL1+), arterial EC(GJA5+FBLN5+DKK2), lymphatic EC (CCL21+TFF3+FABP4), INSR+ tumour EC (INSRhiHSPG2+PLVAP+), and ACKR1+ tumour EC (ACKR1+SELP+IL1R1+)." (PMID 35184398, 2022). "We further demonstrated that CD44 engagement by GPNMB activates in tumor cells the expression of several factors, including chemokines, e.g.: CXCL1, CXCL2, CCL2, CCL5, CCL7, cytokines: IL-6, IL-11, IL-33, and the IL-33 receptor: IL-1RL1, also named ST2." (PMID 34583655, 2021). "In NSCLC patients, expression of IL33 and IL1RL1 was found to be increased in tumor tissue compared to adjacent non-tumor tissue, and this expression was associated with disease clinical stage." (PMID 28119694, 2016). "IL1RL1+ T cells and LAG3+ T cells may play different roles in early or locally progressive HCC, whereas in advanced stages or extensive metastases, their roles may become less significant due to changes in the tumor microenvironment." (PMID 38604154, 2024). "IL1RL1, PCDHGA3, STMN2, and UGT2B11 showed no expression with tumor microenvironment components." (PMID 37985782, 2023).
infection (29 papers, 2010 to 2025). The state of being infected such as from the introduction of a foreign agent such as serum, vaccine, antigenic substance or organism. "IL-33 and IL1RL1 are among the most highly replicated susceptibility loci for A30, and IL-33 has a known role in infection-mediated A susceptibility." (PMID 37573373, 2023). "While ~75% of wild type animals survived infection, both Il1rl1–/–and Il33–/–mice were significantly more susceptible to WNV-E218A infection, displaying reduced survival and enhanced weight loss." (PMID 37983247, 2023). "While intracranial infection of congenic WT animals yielded ~90% survival, Il1rl1–/–mice were significantly more susceptible to infection with survivorship at ~70%." (PMID 37983247, 2023). "Whole-mount immunofluorescence staining showed that the induction of B-cell proliferation in mediastinal FALCs of BALB/c mice was impaired in IL-33R-deficient BALB/c mice (Il1rl1−/−) at day 11 post infection." (PMID 27582256, 2016). "Notably, CpG sites associated with Il4, Il13, Cd200, and Il1rl1 displayed the lowest methylation levels on Day 1 of infection, followed by an increase over time." (PMID 40170749, 2025). "Indeed, il1rl1-/- mice are protected from weight loss, early mortality, and intestinal pathology during the acute stage of infection when mice are infected orally with T. gondii." (PMID 33108405, 2020). "Consistent with changes in DNA methylation levels, expressions of Il4, Il13, Cd200, and Il1rl1 were highest on the first day of infection and gradually decreased over time." (PMID 40170749, 2025). "To quantify this, we examined brain macrophage (CD11b+F4/80+) viability in Il1rl1–/–mice post-infection by flow cytometry." (PMID 37983247, 2023). "To test this, we titered virus from the cortex, hippocampus, cerebellum, brainstem, and peripheral organs of Il1rl1–/–, Il33–/–, and B6/J infected mice at 7 days post-infection (DPI), a timepoint corresponding to peak disease." (PMID 37983247, 2023). "To assess this, we examined the number of brain-engrafted monocytes in B6/J and Il1rl1–/–by flow cytometry following intracranial WNV-E218A infection and observed a marked increase in the number of monocytes in whole brain homogenates at 7DPI." (PMID 37983247, 2023). "We found that at day 12 post-infection, when significant immune populations are first present in the brain, immunity was largely intact in il1rl1-/- mice, measured by IFN-γ+ T cells and INOS+ myeloid cells." (PMID 33108405, 2020). "When we examined brain-resident cell expression of il1rl1, we found that microglia express high levels of il1rl1 in healthy brain tissue, but they downregulate the receptor 20-fold upon infection." (PMID 33108405, 2020). "Plasma IFN-γ levels at day 7 were also intact in il1rl1-/- mice, and are likely enough to control parasite early in infection." (PMID 33108405, 2020). "IL-33, a recently discovered member of IL-1 family, exercising its role as an alarm signal (alarmin) in response to cellular damage induced by infection or injury to alert immune cells expressing the ST2 receptor (IL-1RL1)." (PMID 30564243, 2018). "In summary, IL1RL1 confers protection from infection, which is consistent with its involvement in the Th2 immune response." (PMID 21629437, 2010). "In the state of injury, necrosis, or cell stress, IL-33 is released into the extracellular space and binds to its cognate receptor interleukin-1 receptor-like 1 (IL1RL1), which has been associated with tissue and metabolic homeostasis, inflammation, infection, and cancer." (PMID 34023857, 2021). "Analysis of the Ly6chi population in the liver at 7 dpi after infection with Pru-tdTom showed that a proportion of infected and uninfected cells express iNOS in the Rag1−/−mice, but iNOS levels were markedly reduced in the Rag1−/−; Il1rl1−/− mice." (PMID 33929319, 2021).
infection (continued). "Additionally, parasite levels were equivalent in the brain at day 12 post infection (12DPI) in il1rl1-/- mice in comparison to wildtype mice, further supporting that the control of parasites is intact during the early stages of infection." (PMID 33108405, 2020). "However, at day 21 post-infection, iNOS frequencies were intact in il1rl1-/- mice, in contrast to a significant decrease of iNOS frequency in il1rl1-/- mice at day 28 post infection." (PMID 33108405, 2020). "Additionally, it is possible that a decrease of circulating IFN-γ at day 12 post infection in il1rl1-/- mice has lasting impacts on chemokine and adhesion expression responsible for recruitment of myeloid cells." (PMID 33108405, 2020). "All of these genes except APOE and IL1RL1 have been associated with the regulation of fibrosis and variation in these may regulate risk of pathology irrespective of intensity of infection." (PMID 33659002, 2021). "There were three common DE genes between cattle and sheep at the acute stage of infection: IL1RL1, CHD1 and RASSF1, and 232 common DE genes at the chronic stage of infection." (PMID 34616397, 2021). "IL-33, identified as a ligand for Interleukin 1 receptor-like 1 (IL1RL1, also known as ST2), stimulates and mediates inflammatory responses following infection and inflammation." (PMID 34093543, 2021). "We did, however, note a decrease in T cell numbers in the blood at day 10 post-infection in il1rl1-/- mice, and decreased serum IFN-γ at day 12 post-infection despite intact IL-12p40 levels." (PMID 33108405, 2020). "Moreover, under conditions of cellular stress, such as infection and tumors, IL‐33 mainly binds to helper proteins (IL‐1RAcP) and receptors (ST2/IL1RL1) on the cell membrane, thereby activating cytokines or downstream signaling pathways." (PMID 40860436, 2025). "It is important to mention that decreased immune activation in il1rl1-/- mice, such as decreased IFN-γ production, during the acute or chronic stage of infection, could be beneficial in protecting against immunopathology." (PMID 33108405, 2020). "At 10 days post-infection, no parasite was detected in the peritoneal cavity of infected il1rl1-/- or wildtype animals." (PMID 33108405, 2020). "If microglia normally respond to IL-33 earlier in infection, our results indicate that astrocyte responses to IL-33, or additional MyD88-dependent signals, may compensate for the lack of il1rl1-signaling in microglia." (PMID 33108405, 2020). "To characterize the activation and differentiation states of CD8+ T cells primed without IL-33 signals, we infected WT and Il1rl1−/− mice with LCMV and analyzed their CTLs at day 6.5 after infection." (PMID 31447845, 2019).
cancer (17 papers, 2013 to 2025). A tumor composed of atypical neoplastic, often pleomorphic cells that invade other tissues. "We identified potential novel associations between four inflammatory markers (pro-adrenomedullin, interleukin-23 receptor, prothrombin, and interleukin-1 receptor-like 1) and risk of site-specific cancers." (PMID 38301482, 2024). "There was also a trend towards up-regulation of CA2, DPP4 and IL1RL1 in cancer associated fibroblasts." (PMID 23497279, 2013). "Moreover, the genes HES6, SHISA2, PMP22, and IL1RL1 are primarily associated with the progression of cancer and diseases." (PMID 39336820, 2024). "We and others have shown that the IL-33/Il1rl1 signaling pathway plays HSCs self-renewal and cancer-promoting roles." (PMID 40659660, 2025). "IL-33 binds and activates its receptor IL-1 receptor-like 1 (IL1RL1/ST2) and is associated with inflammation and cancer progression." (PMID 34063627, 2021). "Thus, IL11-stimulated fibroblasts are primed to release IL33 when damaged to activate IL33 pathways in neighboring IL1RL1-expressing fibroblasts and other cells, which include immune cells in cancers." (PMID 36012165, 2022). "Among the proteins differentially present in cancer vs. control were six common to both local and metastatic PDAC: Up—GDF15, TIMP1, and IL1RL1; Down—CCL22, APP, and CLEC1B." (PMID 33334063, 2020). "Six were common for cancer stage (Up: GDF15, TIMP1, IL1RL1; Down: CCL22, APP, CLEC1B)." (PMID 33334063, 2020).
inflammation (9 papers, 2010 to 2024). Aberrant reaction of the microcirculation characterized by movement of fluid and leukocytes from the blood into extravascular tissues. "The dichotomous role of the IL-33/IL1RL1 axis within the context of chronic intestinal inflammation has been previously proposed and may explain the results obtained within the present study regarding the association of the rs3939286 polymorphism of IL-33 with IBD and with specific UC phenotypes." (PMID 23634226, 2013). "Besides, IL-1RL1 (alias ST2) could also induce Th17-mediated airway inflammation." (PMID 31466385, 2019).
cardiovascular diseases (5 papers, 2010 to 2024). "The fact that increased level of IL1RL1 is correlated with poor prognosis in different instances of cardiovascular disease points to a role of soluble IL1RL1 as marker for the severity of the immune response." (PMID 21629437, 2010). "The company Critical Diagnostics in collaboration with the Brigham and Women’s Hospital in Boston has developed a diagnosis kit called Presage that uses soluble IL1RL1 levels for diagnosis and prognosis of cardiovascular disease." (PMID 21629437, 2010). "Increased IL1RL1 isoform B is indicative of an overwhelming immune response that is hard to control and thus leads to unfavorable outcome in cardiovascular disease patients, such as after an MI." (PMID 21629437, 2010). "Many U.S. and international patents protect the use of IL1RL1 for the diagnosis and prognosis in cardiovascular disease." (PMID 21629437, 2010). "Soluble interleukin 1 receptor-like 1 (ST2) is a circulating protein demonstrated to be associated with cardiovascular diseases; however, it has not been studied as a biomarker for peripheral artery disease (PAD)." (PMID 39311197, 2024). "The growth Stimulation expressed gene 2 (ST2) (or interleukin 1 receptor-like 1, also known as IL1RL1) is considered a biomarker of poor prognosis in cardiovascular diseases." (PMID 33355808, 2021).
infectious disease (2 papers, 2024). A disorder directly resulting from the presence and activity of a microbial, viral, or parasitic agent in humans. "The IL-33/IL1RL1 axis plays diverse roles in various infectious diseases, and studies have suggested that it confers a protective effect against Group A Streptococcus infection by enhancing innate immunity." (PMID 38898675, 2024). "FXBL19 targets the IL-33/IL1RL1 axis, crucial in infectious diseases and innate immunity promotion." (PMID 38898675, 2024).
head and neck tumors (1 paper, 2024). "In this study, it was found that IL-1α, IL-1β, IL1R1, IL1RL1, IL1F10, IL33, CASP1, and AIM2 were highly expressed in head and neck tumors, while IL1RN, IL1RAPL1, IL1RAPL2, IL18BP, IL18R1, and IL18RAP were low in expressed, which is consistent with previous literature." (PMID 39461030, 2024).
heart diseases (1 paper, 2025). "Although our results indicate that IL1RL1 rs11685424 is not related to the pathogenesis of PD, this SNP has been associated with respiratory conditions and heart diseases." (PMID 40352809, 2025).